ZBTB7A (zinc finger and BTB domain containing 7A)
Diseases named in the same sentence as ZBTB7A in open-access papers (continued):
Sharing a sentence is not in itself a finding about the gene and the disease.
cancer (continued). "ZBTB7a is a transcriptional repressor that is differentially expressed in a variety of human cancers, in which it is thought to favor tumorigenesis by silencing of the INK4‐ARF locus through histone modification and chromatin remodeling." (PMID 25990945, 2015). "Importantly, the authors found that reduced ZBTB7A expression was associated with later stages of cancer and poor patient survival across cancer types, but also conferred a higher sensitivity to glycolysis inhibition, which could be exploited to develop new treatment options." (PMID 26404381, 2015). "The correlation of expression of each of these polarity and cytoskeletal genes in each dataset revealed that there were significant correlations (P<0.05) for several cytoskeletal or polarity regulatory genes with Bcl6 or ZBTB7A in several cancer types." (PMID 26187947, 2015). "A serial of reports revealed important roles of Zbtb7A in human and mouse adipogenesis, human cancer pathogenesis and cell's determination of B versus T lineage." (PMID 19723341, 2009). "ZBTB7A is required for the regulation of tumor growth in cancers, including GBM." (PMID 36596853, 2023). "Besides its association with multiple physiological processes, such as cell proliferation, metabolism, adipogenesis and hematopoiesis, ZBTB7A plays oncogenic or onco-suppressive roles in several human cancers, depending on the tissue and cancer type." (PMID 37065756, 2023). "The accumulated evidence to date implicates ZBTB7A as a key player in cancer cell fate and thus, we sought to investigate whether ZBTB7A is critical for NEPC cell proliferation and survival." (PMID 37065756, 2023). "Previous reports showed that some miRNAs regulated ZBTB7A expression in cancers." (PMID 35501800, 2022). "According to previous research, ZBTB7A may act as an oncogene or tumor suppressor in a variety of malignancies, depending on the type and genetic context of cancer." (PMID 35501800, 2022). "The function of ZBTB7A in the tumor is controversial and accumulating evidence indicates that ZBTB7A regulates several cell survival, differentiation and death signaling in diverse types of cancers." (PMID 35501800, 2022). "Studies have reported that ZBTB7A plays both proto-oncogenic and tumor suppressive roles that depend on the cancer type and stage-specific situation and that targeting ZBTB7A could be a promising tumor growth inhibition approach." (PMID 35756490, 2022). "Besides, we explored the relationship between ZBTB7A expression and the infiltrating immune cells in 9 cancer types, including BLCA, COAD, LUAD, READ, BRCA, CHOL, HNSC-HPV pos, HNSC-HPV neg, LIHC using the TIMER database." (PMID 33292231, 2020). "There was variability in the expression of ZBTB7A in different types of cancers, which may reflect differences in the data collection methods and the underlying causative mechanisms." (PMID 33292231, 2020). "ZBTB7A is overexpressed in many human cancers, including ovarian, breast, as an oncogene." (PMID 33292231, 2020). "In addition, some opposite functions of ZBTB7A have been reported in other kinds of cancers, such as melanoma and prostate cancer." (PMID 33167891, 2020). "ZBTB7A is an essential factor in regulating different aspects of human cancer." (PMID 33292231, 2020). "Besides, we also found that ZBTB7A mRNA expression was related to the survival in 2 cancers out of 9 cancers, including CHOL and HNSC-HPV pos." (PMID 33292231, 2020). "Further research on the carcinogenic function of ZBTB7A was found that ZBTB7A could affect the survival, proliferation, apoptosis, and migration of cancer cells." (PMID 33292231, 2020).
cancer (continued). "The diverse functions of ZBTB7A in cancer and NAFLD might be due to the commonly elevated glycolysis in cancer, and the metabolic disorder was complicated." (PMID 31998789, 2020). "Furthermore, many reports demonstrated that ZBTB7A was overexpressed in some cancers, acting as tumor promoter involved in the progression of the disease." (PMID 31998789, 2020). "It is therefore speculated that LRF/ZBTB7A potentially mediates the cross-communication between the intrinsic and extrinsic apoptotic pathways, notably in cancer cells." (PMID 31823818, 2019). "Another significant interaction mediating LRF/ZBTB7A functions in cancer is through binding and promoting the signaling of nuclear factor (NF)-κB, a transcription factor with well-known properties in regulating many aspects of cancer, inflammation, and immune responses." (PMID 31823818, 2019). "Zbtb7a expression in several type of cancers is remarkably higher than its in normal tissues." (PMID 28881782, 2017). "In cancer, LRF/ZBTB7A has been reported to act either as oncogenic or as oncosuppressive factor by affecting specific cell processes (proliferation, apoptosis, invasion, migration, metastasis, etc) in opposed ways, depending on cancer type and molecular interactions." (PMID 31823818, 2019). "LRF/ZBTB7A expression also positively correlates with many clinicopathologic parameters of human cancers like tumor size, histological grade, and overall patient survival, findings rendering this molecule a potential biomarker for human cancers, as well as an attractive therapeutic target." (PMID 31823818, 2019). "Other targets of LRF/ZBTB7A-mediated regulation of oncogenesis include Striatin 4 (STRN4), a protein implicated in the progression of various human cancers and protein C-ets-1 (ETS-1), which is overexpressed in several cancers and implicated in cell proliferation, apoptosis, invasion, and migration." (PMID 31823818, 2019). "Recent studies in which PFKP expression was indirectly increase or decrease either via the ZBTB7A transcriptional repressor or by sorafenib have suggested that PFKP might be a suitable drug target for anti-cancer therapies as inhibition of PFKP represses aerobic glycolysis." (PMID 29069720, 2017). "There were significant differences in ZBTB7A expression in cancer tissues from GBM patients with different pathological grades, indicating a positive correlation between ZBTB7A expression and clinical pathological grading." (PMID 40471367, 2025). "Investigated in many cancer types, LRF (ZBTB7A) has either oncogenic or tumor suppressor functions, highlighting its ability to act differently, depending on the existing epigenetic landscape." (PMID 38879530, 2024). "Cancer cells with high SCN phenotype scores showed a strong dependency on RET kinase activity with a high correlation between RET and ZBTB7A dependencies in these cells." (PMID 37065756, 2023). "In order to validate the transcription factor role of ZBTB7A to KLF10, transcriptomic data of kidney para-carcinoma tissue in TCGA and normal kidney tissue in GTEx from GEPIA showed significant positive correlation between KLF10 and ZBTB7A." (PMID 36878898, 2023). "All the discoveries signified that PURPL elevated ZBTB7A’s expression and initiated the PI3K/AKT/NF-κB pathway, hence bringing into full play its substantial cancer-promoting function." (PMID 35012438, 2022). "It is therefore plausible that, at least in some human cancers, LRF/ZBTB7A represents one of the incipient traits rendering cancer cells tumorigenic and ultimately malignant, thus favoring cancer progression." (PMID 31823818, 2019).
cancer (continued). "While this new approach allowed us to confirm the difference in RET dependency between SCN HI and LO cell lines, the ZBTB7A dependency scores alone failed to segregate cell lines into two groups, probably due to its counter roles in cancer." (PMID 37065756, 2023). "Zinc finger and BTB domain-containing 7A (ZBTB7A) is a member of the POK family of transcription factors that plays an oncogenic or tumor-suppressive role in different cancers depending on the type and genetic context of cancer." (PMID 35501800, 2022). "However, ZBTB7A was not correlated with the infiltration levels of CD8 + T cells in nine cancer types." (PMID 33292231, 2020).
tumor (40 papers, 2013 to 2025). "Loss of ZBTB7A inhibited tumor growth in vivo, resulting in a 75% decrease in tumor volume and an 80% decrease in tumor weight." (PMID 35501800, 2022). "Among the 10 survival-related genes included in the signature, the risk-associated genes PWP2 and TGFB1 have been suggested to be associated with GC invasion and metastasis, and ZBTB7A, a protection-associated gene, plays a tumor-suppressive role in GC cells." (PMID 34413861, 2021). "Recently, somatic zinc-finger mutations of ZBTB7A were found at low frequencies (<5%) in a variety of solid cancers suggesting a common mechanism across tumour entities." (PMID 27252013, 2016). "In addition, ZBTB7A acts as a tumor suppressor; the loss of ZBTB7A in a PTEN-deficient environment promotes tumor growth in mouse prostate cancer." (PMID 36596853, 2023). "In this study, we explored the relationship between TMED3 and GBM, including its effects on tumor proliferation, invasion, and metastasis, as well as its interaction with ZBTB7A in GBM development." (PMID 40471367, 2025). "This lncRNA inhibits miR-93-5p and upregulates zinc finger and BTB domain-containing protein 7A (ZBTB7A)—a factor that acts a tumour suppressor." (PMID 38893244, 2024). "The protein expression of EPB41L5 and ZBTB7A was observed in mouse tumor tissues injected with control U343 cells and ZBTB7A-expressing U343 cells using IHC analysis." (PMID 36596853, 2023). "When the expression of ZBTB7A was knocked down, cell migration was significantly increased in ZBTB7A-knockdown U87 cells, and tumor invasion and colony formation were also increased in ZBTB7A-knockdown U87 cells compared with control U87 cells." (PMID 36596853, 2023). "Overall, we discovered the role of a novel tumor suppressor that directly inhibits GBM progression (ZBTB7A) and identified EPB41L5 as a therapeutic target protein for patients with GBM." (PMID 36596853, 2023). "Our study revealed a novel tumor suppressor role for ZBTB7A, which directly inhibits GBM tumorigenesis." (PMID 36596853, 2023). "ZBTB7A negatively regulates GBM tumor progression by directly binding to the promoter of EPB41L5, an important gene involved in cell mobility, and repressing its transcription." (PMID 36596853, 2023). "We demonstrated that ZBTB7A dramatically inhibits GBM tumor growth through transcriptional repression of EPB41L5." (PMID 36596853, 2023). "In our study, ZBTB7A provided insight into the mechanism of a tumor suppressor in GBM, and its deficiency significantly increased the tumor growth of GBM." (PMID 36596853, 2023). "As expected, tumor growth on ZBTB7A-expressing U343 cells was further reduced compared to that in control cells." (PMID 36596853, 2023). "The Zbtb7a gene generates coding mRNAs and exerts its tumor suppressive role, but the non-coding product of Zbtb7a, circPOK, acts as an oncogene in mesenchymal cancers." (PMID 35372031, 2022). "miR-100 targets and suppresses ZBTB7A’s expression, thus cramping tumor cell migration and invasion." (PMID 35012438, 2022). "Nevertheless, there is a different opinion that overexpression of ZBTB7A contributes to GC cells’ cycle arrest, curbs their migration, and steps up their apoptosis, and it displays a remarkable tumor-suppressing function in the context of GC." (PMID 35012438, 2022). "Here, we uncovered that ZBTB7A modulated tumor development through its influence on various typical signaling pathways." (PMID 35012438, 2022). "In contrast, miR-106b exhibited the tumor-suppressive function through regulating ZBTB7A in ovarian cancer." (PMID 33007962, 2020). "This suggests that ZBTB7A plays a vital role in regulating tumor immunity, and therefore influences UCEC prognosis." (PMID 33292231, 2020). "Low ZBTB7A mRNA expression not merely correlates with unfavorable prognosis in UCEC, but also in CHOL and HNSC-HPV cancers, Furthermore, There exist a markedly relationshiop between ZBTB7A and chlinical characteristics for age, race, and tumor stage in UCEC." (PMID 33292231, 2020).
tumor (continued). "Firstly, Using Oncomine and Tumor Immunoassay Resource (TIMER) databases to evaluate the expression of ZBTB7A." (PMID 33292231, 2020). "In contrast, ZBTB7A was also reported as a tumor suppressor in prostate cancer, melanoma, triple-negative breast cancer, and gastric cancer." (PMID 31998789, 2020). "TIMER was also used to explore the relationship between ZBTB7A and tumor immune invasion, and to detect the correlation between the ZBTB7A and the marker genes related to immune infiltration." (PMID 33292231, 2020). "To further explore the effect of ZBTB7A on tumor growth, we detected the tumorigenesis ability through the xenograft tumor model in vivo over 2 weeks." (PMID 33167891, 2020). "ZBTB7A acts as a tumor suppressor by repressing the expression of key genes in tumor glycolysis and negatively regulating TGF-β pathway." (PMID 32774369, 2020). "Next, we investigated the relevance between ZBTB7A expression and the status of tumor-infiltrating immune cells based on the levels of immune marker gene in UCEC tissues through investigation the TIMER and GEPIA databases." (PMID 33292231, 2020). "Recent studies have shown that ZBTB7A is closely related to the tumor microenvironment and immune cell infiltration in prostate cancer." (PMID 33292231, 2020). "Proposed oncogenic mechanisms to achieve increased SOX9 include transcriptional activation by ERG, which is highly expressed in tumours with TMPRSS2:ERG fusions, and loss of Zbtb7a, encoding a protein that antagonizes SOX9 activity." (PMID 29484136, 2018). "These include regulation of SOX9 expression by ERG, which is found in tumours with TMPRSS2:ERG fusions, and loss of Zbtb7a, which encodes a factor proposed to antagonize SOX9 function rather than expression." (PMID 29484136, 2018). "Intriguingly, though, Zbtb7a has been found to behave both as an oncogene and as a tumour suppressor, depending on context." (PMID 29813070, 2018). "Any inactivating alteration of ZBTB7A will likely increase glycolysis, and, thus, helps the tumour cells to produce more energy." (PMID 27252013, 2016). "As an oncogene, ZBTB7A plays a critical role in tumor progression." (PMID 40471367, 2025). "The expression of EPB41L5 was significantly decreased in ZBTB7A-overexpressing tumor tissues." (PMID 36596853, 2023). "It has been reported that ZBTB7A also acts as a key transcription factor in tumor cells, is closely related to the transcriptional regulation of key glycolytic enzymes, and transcriptionally represses GLUT‐3, PFKP, and PKM2 expression, affecting tumor progression and patient prognosis." (PMID 37066523, 2023). "Therefore, we considered the correlation between tumorigenesis and the tumor microenvironment essential for the growth of GBM cells through epigenetic regulation of the target gene with ZBTB7A." (PMID 36596853, 2023). "In addition, GBM tumorigenesis is determined by the secretomes of the tumor microenvironment through epigenetic regulation of corepressors and coactivators by ZBTB7A." (PMID 36596853, 2023). "In addition, ZBTB7A participates in the regulation of tumor immunity, making it a promising EC biomarker." (PMID 35163161, 2022). "Our results demonstrate that ZBTB7A functions as a tumor suppressor in OSCC." (PMID 32083004, 2020). "Functionally, knockdown of ZBTB7A could markedly inhibit tumor proliferation in vitro and in vivo, whereas ZBTB7A overexpression displayed the opposite results." (PMID 33167891, 2020). "Above all demonstrate the function for ZBTB7A in regulating tumor-infiltration of T-helper cells." (PMID 33292231, 2020). "Besides, the expression of ZBTB7A is also related to many clinicopathological parameters, including tumor size, histological grade, and overall patient survival." (PMID 33292231, 2020).